SNORA71D (small nucleolar RNA, H/ACA box 71D)
Synonyms: U71d
Gene: Small nucleolar RNA gene on chromosome 20 (38,433,865 to 38,433,998, reverse strand). Ensembl gene ENSG00000200354.
Gene Ontology:
Biological process: RNA processing
Cellular component: nucleolus
Homologues: Orthologues: macaque SNORA71 (97% identical), guinea pig SNORA71 (81% identical), pig SNORA71 (78% identical). Paralogues in human: SNORA71C (87% identical), SNORA71A (84% identical), SNORA60 (82% identical), SNORA71 (75% identical), SNORA71E (75% identical), SNORA71 (71% identical), SNORA71 (68% identical).